NIF3L1 (NGG1 interacting factor 3 like 1)
Description:
May function as a transcriptional corepressor through its interaction with COPS2, negatively regulating the expression of genes involved in neuronal differentiation.
Synonyms: ALS2CR1; MDS015; CALS-7
Tractability: PROTAC: ubiquitination databases record sites on it; its protein half-life has been measured.
Gene: Protein-coding gene on chromosome 2 (200,888,992 to 200,905,578, forward strand). Ensembl gene ENSG00000196290.
Subcellular location: Cytoplasm; Nucleus
Subcellular location (Human Protein Atlas): Vesicles
Gene Ontology:
Molecular function: identical protein binding; protein binding; RNA polymerase II-specific DNA-binding transcription factor binding
Biological process: positive regulation of DNA-templated transcription; negative regulation of transcription by RNA polymerase II; neuron differentiation; regulation of DNA-templated transcription
Cellular component: cytoplasm; mitochondrion; nucleus
Genetic constraint (gnomAD): Loss-of-function variants: 24 observed, 33.14 expected, observed/expected ratio (o/e) 0.72, 90% interval 0.52 to 1.02. The upper end of that interval is the gene's LOEUF score, 1.02, which puts it in group 4 of 6, group 1 being the genes least tolerant of losing a copy. Missense variants: 445 observed, 482.06 expected, observed/expected ratio (o/e) 0.92, 90% interval 0.85 to 1. Synonymous variants: 157 observed, 185.33 expected, observed/expected ratio (o/e) 0.85, 90% interval 0.74 to 0.97.
Homologues: Orthologues: chimpanzee NIF3L1 (99% identical), pig NIF3L1 (89% identical), dog NIF3L1 (88% identical), rat Nif3l1 (87% identical), mouse Nif3l1 (84% identical), macaque NIF3L1 (83% identical), guinea pig NIF3L1 (69% identical), tropical clawed frog nif3l1 (51% identical), zebrafish nif3l1 (44% identical), Drosophila melanogaster CG4278 (31% identical).
Diseases named in the same sentence as NIF3L1 in open-access papers:
NIF3L1 is named in the same sentence as 12 diseases in open-access papers, as found by Europe PMC text mining. Sharing a sentence is not in itself a finding about the gene and the disease. The quoted sentences say what the papers report.
age-related macular degeneration (1 paper, 2025). Age-related loss of vision in the central portion of the retina (macula), secondary to retinal degeneration. "The complex Linkage Disequilibrium pattern observed encompasses 7 other genes and further research is necessary to see if the sentinel variant rs10931931 identified in this study is indeed driving the causal relationship between NIF3L1 and age-related macular degeneration." (PMID 40883583, 2025).
epilepsy (1 paper, 2024). A brain disorder characterized by episodes of abnormally increased neuronal discharge resulting in transient episodes of sensory or motor neurological dysfunction, or psychic dysfunction. "Surprisingly, we also identified many differential proteins such as UGGT2, SEMG1, PDIA4, ROR1, NIF3L1, and ITIH4, that have not previously been directly reported with epilepsy." (PMID 38585359, 2024).
osteoarthritis (1 paper, 2025). A noninflammatory degenerative joint disease occurring chiefly in older persons, characterized by degeneration of the articular cartilage, hypertrophy of bone at the margins and changes in the synovial membrane. "However, studies about NIF3L1 and CIR1 are rare; we just know that NIF3L1 appears in both osteoporosis and osteoarthritis patients, and CIR1 is a transcription factor that regulates iron acquisition and use." (PMID 40980812, 2025).
osteoporosis (1 paper, 2025). A condition of reduced bone mass, with decreased cortical thickness and a decrease in the number and size of the trabeculae of cancellous bone (but normal chemical composition), resulting in increased fracture incidence. "Additionally, the mRNA relative expression of CIR1, GPR27, and PDE8A were reduced in the osteoporosis group, while NIF3L1 and VPS35 were increased." (PMID 40980812, 2025).
neurological disorder (1 paper, 2015). "However, as a note of interest, these CNVs included the NDUFB3, NIF3L1, PPEF2, CACNA2D1 and GPC5 genes, which are expressed in the brain and/or have been implicated in neurological disorder." (PMID 25585696, 2015).
NIF3L1 also shares sentences with these, for which no sentence is quoted: cancer (2 papers); colorectal adenocarcinoma (1); endometrioid carcinoma (1); immune complex diseases (1); macular degeneration (1); rheumatoid arthritis (1); tumor (1).